IL1B (interleukin 1 beta)
Diseases named in the same sentence as IL1B in open-access papers (continued):
Sharing a sentence is not in itself a finding about the gene and the disease.
coronary artery disease (118 papers, 2008 to 2026). "In patients with coronary artery disease, platelet activation is linked to elevated levels of inflammatory cytokines such as IL-1β, IL-6, and TNF-α." (PMID 40807011, 2025). "The identification of GRP and IL-1β as independent risk factors for CAC underscores the importance of inflammation in the pathogenesis of coronary artery disease." (PMID 40241989, 2025). "Main inflammasome biomarkers that are associated with coronary artery disease progression include IL‐1β, Nucleotide-binding oligomerization domain-like receptor family pyrin domain containing 3 (NLRP3), and caspase‐1." (PMID 39039680, 2024). "Coronary artery disease is associated with increased levels of proinflammatory cytokines such as IL-1β, IL-6, interferon-γ (IFN-γ), and TNF-α." (PMID 38267838, 2024). "Although NLRP3 inflammasome-interleukin (IL)-1β has been implicated in the pathophysiology of coronary artery disease, its roles in cerebral arteriothrombotic micro-circulation disease such as CSVD remains unexplored." (PMID 36676165, 2023). "The PREDIMED sub-study conducted in Spain, using data collected from 285 participants at risk of coronary heart disease, reported a reduction in plasma levels of IL-1β, consistent with our study." (PMID 36297122, 2022). "Recent studies have confirmed that the secretion of IL-1β increases the risk of cardiovascular diseases, with great significance for the clinical diagnosis and condition assessment and monitoring of coronary heart disease." (PMID 35282820, 2022). "A study showed that NLRP3 rs10754558 polymorphism is associated with the occurrence and severity of coronary artery disease and the increase in serum concentration of IL-1β." (PMID 35464402, 2022). "Previous investigations have implicated NETs in coronary artery disease, and the present report correlates systemic inflammation and IL-1β with MPO-DNA complexes, currently considered an established assay for NETosis in vivo." (PMID 31779200, 2019). "Common genetic variations in the IL-1β gene have been shown to influence IL-1 β production and been implicated in the causation of premature coronary artery disease." (PMID 18298837, 2008). "Indeed, anti-inflammatory therapies including anti-IL1β inhibition and colchicine have been studied in randomized controlled trials (RCTs) in patients at risk for and with coronary artery disease (CAD) and have shown reductions in cardiovascular events." (PMID 37296366, 2023). "Moreover, the IL-1β gene, which releases IL-1β as a proinflammatory agent, is associated with cardiovascular diseases, including coronary artery disease, stent restenosis after percutaneous coronary interventions, carotid artery disease, lone atrial fibrillation, and CSFP." (PMID 35773625, 2022). "CANTOS study showed that anti-inflammatory therapy targeting the IL-1β with canakinumab in patients with a stable coronary disease could lead to a 15% lower risk of cardiovascular events than was observed with placebo, but also led to a slightly higher incidence of fatal infections." (PMID 36386333, 2022). "In particular, research has consistently indicated a link between NLRP3 activity and elevated levels of IL-1β and IL-18, correlating with the severity of conditions such as coronary artery disease." (PMID 40564905, 2025). "The prognostic significance of IL-1β has also been explored in decompensated HF, which includes ischemic heart disease as an etiology." (PMID 40428204, 2025). "Studies have shown that patients with coronary heart disease exhibit notably higher levels of succinate and IL-1β compared with healthy individuals, with a positive correlation between succinate and IL-1β levels." (PMID 38933270, 2024). "Clinically, IL-1Ra can be measured as a proxy for IL-1β, and its levels are higher in patients with unstable coronary disease who have a complicated hospital course compared with an uneventful course." (PMID 38256155, 2024).
coronary artery disease (continued). "Higher IL-1β levels are found in the pericardial fluid of patients with ischemic heart disease compared to valvular and congenital heart disease groups." (PMID 38256155, 2024). "In summary, these findings initially suggest an opportunity to reduce the burden of coronary heart disease in patients using either drug targeting IL-1β or other inflammatory inhibitory pathways." (PMID 36873405, 2023). "Compared with healthy adults, the expressions of the NLRP3 inflammasome, ASC, caspase-1, IL-1β, and IL-18 in the serum of patients with coronary heart disease were significantly increased." (PMID 35464402, 2022). "The clinical research CANTOS involving IL-1β neutralizing antibody canakinumab in coronary disease has encouraging findings." (PMID 35379787, 2022). "It was proven that treatment with the anti–IL-1β antibody canakinumab significantly reduced recurrent cardiovascular events in individuals with stable coronary artery disease." (PMID 33466883, 2021). "Anti-inflammatory treatment with IL-1β monoclonal antibodies or intensive statin treatments in patients with coronary heart disease has been shown to reduce the incidence of MACE." (PMID 34378727, 2021). "The CANTOS trial with the monoclonal antibody (Mab) Canakinumab to block proinflammatory cytokine interleukin-1β (IL-1β) was a recent success in treating coronary artery disease." (PMID 33193322, 2020). "The CANTOS trial with the Mab Canakinumab to block proinflammatory cytokine IL-1β was a recent success in treating coronary artery disease." (PMID 33193322, 2020). "The Canakinumab Antiinflammatory Thrombosis Outcome Study (CANTOS) trial demonstrated that inhibiting IL-1β pathway activation significantly reduced coronary artery disease morbidity and mortality in HIV uninfected persons." (PMID 33002093, 2020). "Nuclear translocation of dimeric PKM2 boosts the transcription of IL-1β and IL-6 in LPS-activated macrophages from patients with coronary artery disease." (PMID 32938830, 2020). "The anti-inflammatory effects of testosterone were demonstrated when it reduced the expression and secretion of TNF-α and IL-1β in monocyte-derived macrophages obtained from patients with coronary heart disease." (PMID 31500378, 2019). "Of interest, STAT3 is required for Flt3-dependent formation of DCs from bone marrow derived cells, and plays an important role in production of IL-1β, IL-6, and TNFα in macrophages of humans with coronary artery disease." (PMID 29800237, 2018). "Cardiovascular diseases, including atherosclerotic heart disease, coronary heart disease (CHD), congestive heart-failure (CHF), and other cardiovascular diseases, have been associated with elevated levels of IL-1β, IL-6, TNF-α, and IFN-γ." (PMID 24995360, 2014). "RA patients had significantly higher levels of IL-1β, IL-6, and IL-18 compared to controls.Disease activity (DAS-28) and RF positivity were major risk factors for ischemic heart disease in RA.Better disease control and remission can reduce cardiac complications in RA patients." (PMID 41179568, 2025). "Future research should focus on elucidating colchicine’s effects on inflammatory cells concerning NLRP3 inflammasome; assessing potential benefits and risks in managing ischemic heart disease and developing therapies targeting IL-1β and NLRP3 pathways or inhibiting inflammasome activity." (PMID 40149903, 2025). "Notably, all clinical trials that obtained significant cardiovascular benefits (CANTOS, COLCOT, and LoDoCo2) so far in terms of anti-inflammatory treatment for coronary heart disease target the NLRP3/IL1β inflammatory axis." (PMID 38281937, 2024). "This suggests that NLRP3/IL1β may be important for effective anti-inflammatory therapy as well as further improving the prognosis of ischemic heart disease." (PMID 38281937, 2024).
coronary artery disease (continued). "Therefore, CANTOS (Canakinumab Anti-inflammatory Thrombosis OutcomeStudy) study was designed to confirm the independent role of inflammation inatherosclerosis, and to explore inhibition of IL-1β as a therapeuticoption for coronary artery disease." (PMID 39076864, 2023). "IL-1β inhibition by canakinumab evidently reduces inflammation in patients with atherosclerotic disease, and reduces recurrent cardiovascular events in stable patients with coronary artery disease." (PMID 37593179, 2023). "In KD, anti-IL-1β treatment may help prevent coronary artery disease, although more studies are required on this topic." (PMID 36569831, 2022). "Another pattern has been reported in the population with ischemic heart disease in Western Australia, where IL1B + 3954 T > C (rs1143634) SNPs were studied and TT homozygotes had larger waist circumference and the largest value was noted in individuals with two copies of the IL1A:IL1B T:T haplotype." (PMID 35139823, 2022). "Finally, it is also worth noting that after IL-1β blockade with canakinumab in patients with ischemic heart disease, in the CANTOS trial, IL-18 remained as the main proinflammatory factor associated with increased CV risk." (PMID 35160217, 2022). "Knockout studies of USF1 in mice have been shown to enhance cholesterol efflux in macrophages and downregulate secretion of pro-inflammatory cytokines such as MCP-1 and IL-1β and USF1 variants in humans have been associated with familial combined hyperlipidemia and coronary artery disease." (PMID 34027315, 2021). "In 2017, the CANTOS trial demonstrated that administration of an antibody directed against the pro-inflammatory cytokine interleukin-1β (IL-1β) reduced cardiovascular events in patients with coronary artery disease (CAD), thereby providing first evidence for effectiveness of an immunotherapy in CVD." (PMID 35097027, 2021). "Recently, the results of the Canakinumab Anti-inflammatory Thrombosis Outcome Study (CANTOS, targeting the interleukin-1β) trial show conclusive proof that reduction of inflammation by inhibiting the IL-1β pathway activation can significantly lower coronary artery disease morbidity and mortality." (PMID 33780445, 2021). "This association is further underscored by recent reports describing that glucose over-utilization drives the excessive production of IL-6 and IL-1β by monocytes and macrophages derived from patients with coronary artery disease, by a process that is dependent on redox-sensitive STAT3 signaling." (PMID 32350546, 2020). "There is also an important link between IL‐1β and coronary artery disease (CAD) in RA." (PMID 33204425, 2020). "IL-1β inhibition with canakinumab has recently been shown to reduce cardiovascular events in patients with coronary arterial disease and has also been shown to decrease immune activation in treated HIV patients, but there are concerns about its safety, particularly infectious complications." (PMID 30161247, 2018). "However, in ischemic heart disease patients, atherosclerotic coronary arteries synthesize and express significant IL-1β within the endothelium compared with controls." (PMID 28069066, 2017). "Epicardial adipose tissue expresses and secretes several bioactive molecules including interleukin (IL)-1, IL-1β, IL-6, IL-8, and IL-10, the levels of these interleukins were found as significantly higher in subjects with coronary artery disease when compared to healthy subjects." (PMID 25887962, 2015). "An additional clinical trial was recently launched using canakinumab with the hypothesis that IL-1β inhibition will reduce major cardiovascular events in patients with preexisting coronary artery disease (CAD)." (PMID 25010102, 2014). "Sixth, it is conceivable, that patients with a higher inflammatory status and a polymorphism in IL1B or IL1RA have stronger association to coronary heart disease than patients without inflammation." (PMID 23029154, 2012).
coronary artery disease (continued). "Therefore, pharmacological inhibition of the cytokine IL-1β might be considered as a novel strategy to prevent or reverse the deterioration of the bone vascular function in ischemic heart disease." (PMID 34172720, 2021). "Data from the CANTOS trial showed that neutralizing IL‐1β, a prominent SASP member, with canakinumab benefited patients with coronary artery disease (CAD)." (PMID 40375481, 2025). "In patients with coronary artery disease (CAD), quercetin has decreased the transcriptional activity of NF‐κB and reduced serum levels of IL‐1β." (PMID 41195524, 2025). "Understanding the mechanisms of post-ischemic inflammation, particularly involving IL-1β and NLRP3, is crucial for developing effective therapies to mitigate tissue damage and improve prognosis in ischemic heart disease patients." (PMID 40149903, 2025). "Lutein is swallowed by blood mononuclear cells and it is capable to inhibit both gene expression and secretion of IL-6, IL-1β, and tumor necrosis factor (TNF) in stable coronary artery disease patients." (PMID 37655002, 2023). "In two studies among patients with coronary artery disease, it reduced the concentrations of pro-inflammatory interleukins (ILs) 8 and 12; interferons, including interferon gamma (IFN-γ); and IL-1β." (PMID 38138886, 2023). "Based on the findings of the present study, the levels of SAH, IL-1β, Hcy, TNF-α and BDNF can predict the severity of coronary heart disease." (PMID 35282820, 2022). "Based on this, this study aimed to explore the expression of serum SAH, IL-1β, Hcy, TNF-α, BDNF in coronary heart disease and the relationship with the degree of coronary artery disease." (PMID 35282820, 2022). "In the present manuscript, we aim at exploring the link between EAT-secreted IL-1β, atrial remodeling, and POAF in a population of coronary artery disease (CAD) patients undergoing cardiac surgery." (PMID 35721500, 2022). "In coronary artery disease, statins especially atorvastatin, can reduce expression of the NLRP3 inflammasome as well as downstream factors IL-1β and IL-18." (PMID 31354731, 2019). "Interleukin family was also predicted to be related to coronary artery disease, including IL 6, IL4, IL10, IL1A, and IL1B." (PMID 29861771, 2018). "In case of suffering from coronary artery disease (CAD), the epicardial adipose tissue displayed significantly higher levels of chemokine (MCP-1) and several inflammatory cytokines (IL-1β, IL-6, IL-6sR, and TNF-α), comparing to subcutaneous adipose tissue." (PMID 28757877, 2017). "In the blood samples draw from patients with coronary artery disease, the peripheral blood mononuclear cells express higher levels of NLRP3 inflammasome and the inflammasome‐dependent IL‐1β and IL‐18 cytokines when compared with the control patients." (PMID 28470940, 2017). "The neutral result from the IL1β analysis in the present study is notable given that IL1β is upstream of IL6R, and previously reported evidence supports a protective effect of canakinumab for patients with coronary disease." (PMID 37914784, 2023). "In this study, we firstly found that arterial serum of Coronary Heart Disease (CHD) patients contained significantly higher succinate and interleukin (IL)-1β than Health control (HC) subjects, and succinate was positively correlated with IL-1β." (PMID 35273600, 2022). "However, there are few studies on the expression of serum SAH, IL-1β, Hcy, TNF-α, and BDNF in coronary heart disease and their relationship with the extent of coronary artery stenosis." (PMID 35282820, 2022). "In patients with coronary artery disease (CAD), adiponectin mRNA expression was markedly decreased in EAT, whereas multiple pro-inflammatory adipocytokines mRNA expression, including chemerin, IL-1β, IL-6 and TNF-α, were significantly increased." (PMID 27352781, 2016).
coronary artery disease (continued). "It has been shown that EAT produces inflammatory mediators such as interleukin (IL)-6, IL-1b, tumor necrosis factor (TNF)-a, and monocyte chemotactic protein (MCP-1) in patients with significant coronary artery disease and expresses mRNAs of adiponectin, resistin, leptin, IL-6, TNF-a, and CD-45." (PMID 23762053, 2013). "Interestingly, irrespective of CH, IL-1β inhibitors have already been found to improve cardiovascular outcomes in patients with stable coronary artery disease." (PMID 36835370, 2023). "In patients with coronary artery disease, the local expression of chemokine (monocyte chemotactic protein 1 (MCP1)) and inflammatory cytokines (IL-1β, IL-6, and TNF-α) was observed with significant changes in MCP1, IL-1β, IL-6, TNF-α mRNA, and protein in the epicardial adipose stores." (PMID 36768479, 2023). "Here, we aim at exploring the link between EAT-secreted interleukin (IL)-1β, atrial remodeling, and POAF in a population of coronary artery disease (CAD) patients." (PMID 35721500, 2022). "In addition to elevation of the proinflammatory cytokines IL1β, TNF-α and IL-6, exercise may reduce C-reactive proteins in patients with coronary arteriosclerosis and Type II T helper cytokines (IL-5 and IL-13) in asthmatic BALB/c mice." (PMID 32778140, 2020). "Thus, the purpose of this study was to compare the plasma NGAL, MMP-9, IL-1β, and hs-CRP levels in different clinical presentations of coronary heart disease (CHD) and to evaluate the relationship between those biomarkers and the severity of coronary stenosis in patients without kidney disease." (PMID 31387110, 2019). "However, the relationship between GRP, IL-1β, and coronary artery calcification (CAC) in patients with suspected coronary artery disease (CAD) remains unclear." (PMID 40241989, 2025). "Although many studies have shown the release of IL-1α and IL-1β on AMI experimental models, the increase in IL-1 plasma levels in AMI patients was not systematically highlighted, some studies showing values ​​comparable to those of patients without coronary disease." (PMID 34180324, 2021).